IDO1 (indoleamine 2,3-dioxygenase 1)
Diseases named in the same sentence as IDO1 in open-access papers (continued):
Sharing a sentence is not in itself a finding about the gene and the disease.
tumor (continued). "Inhibition of indoleamine-2,3-dioxygenase 1 (IDO1), a key enzyme regulating tryptophan catabolism to the AhR ligand (AhRL) kynurenine, has been proposed to abrogate tumor intrinsic malignant signaling and enhance anti-tumor immunity." (PMID 38339226, 2024). "Since IDO1 inhibitors have been proven to reduce Tregs within the tumor microenvironment, we explored the potential of combining DSP-0509 with an IDO1 inhibitor to enhance the anti-tumor activity of DSP-0509 while simultaneously reducing Tregs." (PMID 39346737, 2024). "Drug targeting of IDO1 and TDO2 reversed the functional inhibition of NK cells by CAFs, thereby reducing tumor resistance to trastuzumab." (PMID 39294728, 2024). "Of note, the T-cell suppressive proteins IDO1, VISTA and TIM-3 also had higher expression in tumor-sparse regions." (PMID 39001353, 2024). "Specifically, IFN-γ upregulates IDO1 in GBM tumor cells and tumor-derived extracellular vesicles (EVs)." (PMID 39346924, 2024). "Alongside TILs, the expression of immune evasion molecules in the tumor microenvironment (TME), like programmed death-ligand 1 (PD-L1) and the indoleamine-2,3-dioxygenase enzyme 1 (IDO1), has been demonstrated to negatively influence TNBC prognosis." (PMID 38591056, 2024). "Activation of AhR by KYN, a product of IDO1 and TDO2, prompts the generation of immune-tolerant dendritic cells (DCs) and regulatory T cells, which together shape a tumor immune microenvironment incapable of recognizing and destroying cancer cells." (PMID 38887298, 2024). "This is supported by our analysis showing a correlation between high IDO1 and high CXCL10; the latter IFN-γ-related chemokine has a pivotal influence on cytotoxic T cell tumor recruitment and ICI response." (PMID 38632994, 2024). "The high expression of IDO1, a gene expressed in KIT+ GIST tumor cells, was identified as an important mechanism for imatinib resistance." (PMID 38443340, 2024). "The overexpression of IDO1/TDO2 and the consequent accumulation of KYN suppress anti-tumor immunity by promoting the differentiation of Tregs and MDSCs, which in turn, inhibit the activity of effector CD8+T cells and NK cells." (PMID 39911818, 2024). "Protein expression predominantly clustered within high-density tumor cell regions, notably with AhR and IDO2 demonstrating markedly elevated levels compared to IDO1 and TDO2." (PMID 38951170, 2024). "Here, we sought to analyze data acquired from different databases to investigate IDO1 expression in HNSCC tumors and its correlation with patient survival, drug response, and tumor immune profile." (PMID 38736462, 2024). "Recent bioinformatics analyses have also shown that a variety of tumor markers are correlated with tumor immune infiltration in HNSCC, such as PER3, IDO1, MYL1 and HRPT1." (PMID 38937712, 2024). "In IDO1-SOE mice, serum KP activity and VEGFA concentration were increased accompanied by a rise in the expression of CD34, ATF4, IDO1, and VEGFA in tumor tissues, with the most significant uplift observed in ATF4 and IDO1 expression." (PMID 39065567, 2024). "IDO1 is positively correlated with CD274, TNFRSF9, TNFRSF4, PDCD1LG2, IDO2, and CD48 in many tumor types." (PMID 38539263, 2024). "The dual IDO1/TDO2 inhibitor, STS, effectively boosts the anti-tumor effects of the PD1 antibody in CRC." (PMID 38462620, 2024). "A multitude of cancer cells constitutively express or upregulate IDO1, TDO2, or both, and coerce stromal and tumor-infiltrating immune cells to express IDO1, thus supporting evasion of immunosurveillance." (PMID 38473776, 2024).
tumor (continued). "The expression of IDO1, TDO2, and other enzymes in the kynurenine pathway varies widely among different tumor types and even among patients with the same type of cancer." (PMID 39911818, 2024). "Sodium Tanshinone IIA Sulfonate (STS) inhibits both IDO1 and TDO2, restraining tumor growth and enhancing the anti-tumor activity of PD1 antibodies." (PMID 38462620, 2024). "Gene expression analysis using the nCounter system showed higher expression of tumor immunity‐related genes, such as PD‐L1, LAG3, and IDO1, in PTCL‐TBX21 than in PTCL‐GATA3." (PMID 38234210, 2024). "In the tumor microenvironment (TME), IDO1 is expressed by cancer and stromal cells (such as tumor-associated macrophages and fibroblasts), endothelial cells, and some immune cells [such as dendritic cells and other antigen presenting cells (APC)]." (PMID 38736462, 2024). "The combination of an IDO1 inhibitor (BGB-5777 or 1-methyl-tryptophan), PD-1 blockade and irradiation significantly increased OS and resulted in long-term tumor control in 30–40% of mice with advanced GB." (PMID 38473776, 2024). "TIM-3 and LAG-3 were co-expressed with markers like PD-L1, B7H3, IDO-1, and VISTA, indicating a role in immune regulation within the tumor microenvironment." (PMID 39769271, 2024). "Our study successfully proves that the drugs encapsulated within the NBs are preferentially released under the altered redox conditions commonly found in the tumor microenvironment, thereby inducing cell death, promoting ICD, and inhibiting IDO1." (PMID 38591056, 2024). "Sertaconazole nitrate dose-dependently inhibits IDO1 expression in CRC cells, promoting autophagy and apoptosis and inhibiting tumor growth." (PMID 38462620, 2024). "Direct inhibition of IDO1 and TDO2 is an alternate strategy to decrease kynurenine production and target tumor immune evasion." (PMID 38339226, 2024). "What’s more, immunoregulatory enzymes, such as IDO1 and IL4I1, also created and sustained the tumor-tolerant microenvironment, which is expressed either by the tumor cells or by immune cells." (PMID 37434155, 2023). "In the local tumor microenvironment, CTLA-4 expression has been seen to upregulate IDO1, which reciprocally promotes T-reg activation." (PMID 36879122, 2023). "We evaluated the effect of administering the orally bioavailable IDO1/TDO2 inhibitor AT-0174 alone and in combination with an anti-PD1 antibody on tumor growth and survival." (PMID 37226257, 2023). "A key question about tumor-specific IDO1 expression centers on its transcriptional regulation since the involvement of IFN-independent pathways driving IDO1 expression may open up new opportunities of manipulating tryptophan metabolism in the tumor microenvironment (TME)." (PMID 37196768, 2023). "IDO1 promotes tumor development through immunosuppression, while TDO is connected with tumor proliferation and metastasis." (PMID 38264667, 2023). "Therefore, inhibiting IDO1 during HSV-1 virotherapy could play dual roles by modulating the immunosuppressive TME and enhancing viral replication in the tumor cells, which provided us with the rationale to combine IDO1 inhibitor Navoximod with HSV-1 oncolytic virotherapy for HCC treatment." (PMID 37296221, 2023). "This is further supported by the increased expression of the anti-tumor immunity genes PDL1, CD155 (PVR), CEACAM1, LGALS9, and IDO1, all of which antagonize T cell responses via their interaction with inhibitory receptors." (PMID 36680216, 2023). "As TRP is one of the critical components required for T-cell survival, a first mechanism involves the overactivation of IDO1 and/or TDO to deplete TRP within the local tumour microenvironment rapidly." (PMID 37041200, 2023). "The degradation of Tryptophan to Kynurenine is catabolized by tryptophan enzymes, including IDO1, IDO2, TDO2, and IL4I1, which up‐regulate PD‐L1 expression and promote tumor suppressive microenvironment in various cancers." (PMID 37148546, 2023).
tumor (continued). "IDO1, NOX1, CXCL3, IL1RL2 and NOS2 were upregulated, as their expression levels were lower in the healthy group and higher in the tumor group." (PMID 36911403, 2023). "ASPN in turn promoted upregulation of IDO1 and KYNU in CEFs, which induced cytocidal effects against CD8+ T-cells and promoted tumor spreading." (PMID 37876966, 2023). "Overall, it was concluded that the combination of increased tumor COX-2 and IDO1 in the microenvironment contributed substantially to the poor prognosis and enhanced metastasis formation in vitro and in vivo." (PMID 37296860, 2023). "Theragnostic biomarkers like IDO1, s-CTLA-4, IFN-γ, TNF-α and IL-2 have been studied in various tumors, and seems to hold significant potential in mapping the tumor microenvironment and predicting response to ICPIs." (PMID 36879122, 2023). "Our experimental data unequivocally demonstrated that the most potent bifunctional inhibitor, NK3, directly bonds to IDO1 and STAT3, exhibiting potent in vivo antitumor efficacy in both CT26 tumor-bearing mice and athymic nude mice." (PMID 37630387, 2023). "Indoleamine 2,3 dioxygenase 1 (IDO1) is one of the immune checkpoint blockade genes and is highly expressed in many types of tumor cells; it is the most well studied of the enzymes that initiate tryptophan’s catabolism into kynurenine (Kyn)." (PMID 37999261, 2023). "We found that several protein biomarkers, most notably panCK, IDO1, CD44, and Ki-67, were expressed at higher levels in responders’ tumor compartments; however, in the stroma, SMA, Fibronectin, CD4, and CD27 were the most differentially expressed." (PMID 37153589, 2023). "We evaluated the IHC staining of Trp‐catabolizing enzymes, including IDO1, IDO2, TDO2, and IL4I1, in tumor cells." (PMID 37148546, 2023). "In tumor-repopulating cells (TRC), CD8+ T cells induced the production of kynurenine consistent with the high level of IDO1 expression." (PMID 37296860, 2023). "Another system of nanoparticles can inhibit the indoleamine 2,3-dioxygenase 1 (IDO1) pathway and induce immunogenic cell death to enhance DC maturation, increase the number of CTLs, and decrease the number of Tregs in tumor tissues." (PMID 37443821, 2023). "In a phase I trial, the infusion of EGFRvIII-targeting CAR-T cells led to an adaptive immunosuppressive tumor response characterized by FOX3P+ Treg infiltration and the upregulation of immunosuppressive markers, including IDO-1, IL-10, PD-L1, and TGF-β." (PMID 36768342, 2023). "EBVaGCs also displayed a higher expression of anti-tumor immunity factors (PDL1, CD155, CEACAM1, galectin-9, and IDO1)." (PMID 36680216, 2023). "A cluster of dendritic cells, exclusive to the dpNFs, were enriched for immune checkpoint modulators, IDO1 and PD-L1, which also act to impair CD8+ T cells while also inhibiting AMPK signaling, a tumor suppression pathway." (PMID 37817770, 2023). "Indoximod, an inhibitor of indoleamine 2,3-dioxygenase 1 (IDO1), is an immunometabolic adjuvant capable of enhancing immune cell infiltration within the tumor, and thereby effectively transforms cold tumors into a hot, immunologically active state." (PMID 37373192, 2023). "Indeed, the expression of IDO1 in tumor cells was an important driver in the development of the concept that tryptophan depletion in cancer could inhibit anti-cancer immune function and ergo, IDO1 inhibitors would theoretically promote immune defense (especially T cell responses) against cancer." (PMID 37196768, 2023). "This is mainly because chemotherapy leads to the production of IFN-Is in tumor cells and upregulation of the effect of IFN on IDO1." (PMID 37670034, 2023). "The expression of IDO1 by cancerous cells or cells in the immediate environment can inhibit T effector CD8+ cells, thus maintaining and promoting tumor growth." (PMID 37296860, 2023).
tumor (continued). "IDO1, IDO2, and TDO2 contribute to the noteworthy local catabolism of Trp, and these enzymes, along with PD‐L1, play a crucial role in tumor immune escape." (PMID 37148546, 2023). "We identified a higher percentage of IDO1+ cells among CD68+ and 163+ TAMs in tumour tissue than in healthy adjacent tissue (t test, p < 0.01)." (PMID 35963900, 2023). "Indoleamine 2,3-dioxygenase 1 (IDO1), an interferon-inducible enzyme, contributes to tumor immune intolerance." (PMID 37087488, 2023). "In parallel, STING agonists have the potential to induce the expression of inhibitory molecules, such as programmed death-ligand 1 (PD-L1) and indoleamine 2, 3-dioxygenase 1 (IDO1), which counteract the tumor-suppressive effects." (PMID 37673917, 2023). "In our co-culture model of tumor cells with iNKT cells, we observed IFN-γ-dependent induction of IDO1 expression in both tumor cell lines, albeit at different levels." (PMID 37444608, 2023). "Importantly, in a similar fashion, when evaluating for QA, although IDO1 inhibition resulted in a decrease in QA, biologically relevant concentrations were maintained in the tumor, suggesting a more specific, downstream enzyme may be a more relevant target to attenuate the accumulation of QA." (PMID 36927729, 2023). "Alternative checkpoints, such as v-domain immunoglobulin inhibitory T-cell activation (VISTA) and indoleamine 2, 3-dioxygenase 1 (IDO1), inhibit the tumor-killing function of T cells in addition to PD-L1 and CTLA-4." (PMID 36810098, 2023). "Tumour-biased monocytes upregulate c-FLIP, which in turn activates an immune suppressive program, partially by NF-κB activation, including IL-10, IDO-1, and PD-L1 expression." (PMID 36161514, 2023). "Application of the IDO1 inhibitor LW106 resulted in the substantial elevation of Teff infiltration and reduced recruitment of Tregs, and in xenograft tumor models resulted in the reduced proportion of CSCs." (PMID 38144305, 2023). "Similar to IDO1, TDO is expressed in several cancers, including brain, lung and breast cancers, and has been reported to induce immunomodulation while promoting tumour immune resistance and proliferation." (PMID 37644823, 2023). "IDO1- and TDO2- mediated degradation of tryptophan by cancer cells is a driver of immune suppression in the tumor microenvironment through recruitment and activation of myeloid-derived suppressor cells (MDSCs) and induction of anergy of CD8+ T cells." (PMID 36900311, 2023). "Early lung adenocarcinoma tissue, for example, showed no expression of PD-L1, although it was expressed in a subgroup of patients with the highest density of tumor-infiltrating CD8+ cells, where it was located together with high IDO1 levels." (PMID 37296860, 2023). "Indoleamine-2,3-dioxygenase 1 (IDO1) and signal transducer and activator of transcription 3 (STAT3) have emerged as significant targets in the tumor microenvironment for cancer therapy." (PMID 37630387, 2023). "LY3381916 combined with PD-L1 inhibitor presented maximal inhibition of IDO1 activity and increased CD8+ T cells infiltration in tumor tissue." (PMID 36798123, 2023). "With RNA‐sequencing, IL‐1β enhanced a range of immune inhibitory molecules expression on tumor cells, including CD274, PDCD1LG2, and IDO1." (PMID 37009412, 2023). "The endothelial expression of IDO1 is mainly induced by IFN-y, which is secreted in the tumor microenvironment." (PMID 36830609, 2023). "Based on IHC expression of immune co-inhibitory molecules in our cohort, tumor cells of SCLC were found to be poor immuno-expresser of PD-L1 and IDO1, while CTLA-4 immunolabelling was seen in a fair number of cases." (PMID 36879122, 2023). "Anti-tumor cells secrete IFN-γ that induces genomic instability and/or immune evasive gene expression signature in malignant cells (including PDL1 and IDO1)." (PMID 36774484, 2023).
tumor (continued). "GPC3-CAR T cell treatment together with C1632, the inhibition of Lin28, which targets IDO1 and PDL1, led to enhanced anti-tumor activity in a HCC xenograft mouse model." (PMID 37006306, 2023). "Conversely, IDO1 knockdown restored the percentage of Granzyme B+ CD8+ T cells and reduced the frequency of CD25+FOXP3+ CD4+ T cells within tumor tissues derived from USP14-overexpressing cancer cells." (PMID 37830596, 2023). "These receptors promote xenobiotic metabolism by inducing the cytochrome enzymes, and they induce IL-6, which can induce further IDO1, IDO2 or TDO in malignant cells or tumor lines." (PMID 37296860, 2023). "N-benzyl/aryl-substituted tryptanthrin, a dual inhibitor of IDO and TDO, can directly interact with IDO1, IDO2, and TDO to block the canine urine pathway and promote the proliferation of T cells, ultimately inhibiting the growth of tumor cells." (PMID 37924140, 2023). "We demonstrated that the ratios of Trp/Kyn in both plasma and tumours were markedly increased in the EPA group, which were further boosted by Epacasome-2, suggesting the potent suppression of IDO1 activity in vivo." (PMID 37945606, 2023). "The combination treatment of Abrine and anti-PD-1 antibody has a synergistic effect on suppressing the tumor growth through up-regulating CD4+ or CD8+ T cells, down-regulating the Foxp3+ Treg cells, and inhibiting the expression of IDO1, CD47, and PD-L1." (PMID 37334368, 2023). "IDO1 and IDO2 are members of tryptophan catabolic pathways expressed by tumor cells and tumor microenvironment cells (dendritic cells, macrophages, endothelial cells, tumor-associated Fibroblasts)." (PMID 38260202, 2023). "It is important to note that when using IDO-1 inhibitors in CC therapy, the positivity rate of IDO-1 in this tumor varies between 52 and 100%." (PMID 37626777, 2023). "Pharmacologic inhibition of IDO or deletion of Ido1 gene induces differentiation of inflammatory Ly6c+CD103+ DCs in mice, promoting anti-tumor T-cell response and inhibiting tumor growth." (PMID 38008741, 2023). "Tryptophan catabolism, through IDO1, IDO2, and TDO2, has been well characterized in the context of GBM and seems to contribute to both immunosuppression and tumor growth." (PMID 36768342, 2023). "In this study, we developed a ROS-responsive nanodrug with chemical conjugate with IDO1 inhibitor 1-MT and physical encapsulation of ICD inducer PTX for tumor synergetic chemoimmunotherapy." (PMID 36927803, 2023). "A subsequent study has demonstrated that navoximod, a dual IDO1/ TDO inhibitor, induces a powerful antitumor immune response and inhibits tumor progression when combined with anti-PD-L1 antibodies." (PMID 37924140, 2023). "Like IDO1, TDO2-mediated Kyn promotes tumor immune suppression through AhR-signaling in various cancer types." (PMID 37876966, 2023). "The four GEO datasets and our clinical samples confirmed that the expression levels of CXCL10, IDO1, and MAB21L2 were significantly higher in tumor tissues than in control tissues (P < 0.05)." (PMID 37596528, 2023). "The tumor region of the CR patient indicated higher levels of VISTA, CD45, IDO1, and S100B while S473 expression was found to be decreased." (PMID 37153589, 2023). "Tumor ROIs in BM-LUAD expressed higher expressions of CD14, CD163, GZMA, BCL-6, BAD, BCLXL, 4-1BB, VISTA, and IDO1." (PMID 37061716, 2023). "The modulation of the immunosuppressive microenvironment with the inhibition of IDO1 and JQ1, a drug decreasing the expression of PD-L1 by tumor cells, improved the immunotherapy treatment of GBM in mice." (PMID 37443821, 2023).